ENSG00000296774 (novel transcript)
Gene: Long non-coding RNA gene on chromosome 8 (94,233,585 to 94,234,465, reverse strand). Ensembl gene ENSG00000296774.
Gene Ontology:
Biological process: SRP-dependent cotranslational protein targeting to membrane, signal sequence recognition
Cellular component: signal recognition particle, endoplasmic reticulum targeting